IL6 (interleukin 6)
Diseases named in the same sentence as IL6 in open-access papers (continued):
Sharing a sentence is not in itself a finding about the gene and the disease.
periodontitis (continued). "Moreover, another study also concluded that CU decreases alveolar bone loss in experimental periodontitis in rats via suppressing the expression of RANKL/RANK/OPG and possesses anti-inflammatory properties through the reduction of pro inflammatory cytokines TNF-a and IL-6." (PMID 35453272, 2022). "Two pivotal inflammatory mediators in thyroid disorders, IL-6 and TNF-α, also play a role in inflammation and tissue destruction in periodontitis." (PMID 36359775, 2022). "Increased levels of IL-6 and MMP-8 have been observed in the saliva of patients with chronic periodontitis." (PMID 36275775, 2022). "The present study analyzed salivary levels of IL-1β, IL-6, MMP-8, and IL-10 in periodontally healthy subjects and stage III periodontitis individuals." (PMID 35368315, 2022). "Patients with periodontitis exhibit an elevated level of systemic pro-inflammatory mediators, which include CRP, TNFα, IL-1β, IL-6, as well as increased neutrophil numbers in the blood." (PMID 35874771, 2022). "In addition, other inflammatory mediators in periodontitis, such as IL-1β, IL-6, tumor necrosis factor-α, etc., can be secreted into the blood to activate the systemic immune response, which may lead to tissue destruction in other organs to release DAMPs-derived cfDNA." (PMID 36498477, 2022). "In this study, periodontitis patients with hypertension showed obviously higher hs-CRP and IL-6 levels compared with patients with periodontitis alone (P < 0.05)." (PMID 35813436, 2022). "The gene expression analysis by real-time PCR revealed that the mRNA levels of IL-6 and CXCL2 were significantly (p<0.05) higher in gingival biopsies from periodontitis patients than in the gingiva of periodontally healthy individuals." (PMID 34024010, 2022). "Both IL-6 and PGE2 have been identified as mediators of bone resorption and have been found to promote resorption of the alveolar bone in patients with periodontitis by stimulating the osteoclastic activity." (PMID 35660956, 2022). "The salivary levels of miR-1246, IL-1β, IL-6, IL-17, TNF-α, MMP-1, MMP-8, and TIMP-1 and the periodontal indexes PLI, GI, PD, and AL in the chronic periodontitis group were significantly higher than those in the healthy control (P < 0.05)." (PMID 35942384, 2022). "We found that the mRNA expression of IL-1β, IL-6, and TNF-α in the periodontitis group was, respectively, 2.59-, 5.23-, and 2.29-fold than that of the control group." (PMID 35340409, 2022). "In contrast, IL-6, IL-1β, and TNF-α exhibited strong staining in the periodontitis group, suggesting that the periodontitis model had been well established." (PMID 35340409, 2022). "The combination of IL-6 and MMP-8 showed, for periodontitis vs. healthy gingiva, a high sensitivity of 94% and a specificity of 100%." (PMID 33916672, 2021). "Regarding intestinal tissue analyses, higher levels of IL-1β, IL-4, IL-6, IL-17A, IL17F, IL-21, IL-31, IL-33 and sCD40L were found in patients with IBD and periodontitis." (PMID 34501547, 2021). "Here, the serum‐based three different cytokines (IL‐1β, IL‐6, TNF‐α) showed up‐regulated expression in periodontitis, which were consistent with previous studies." (PMID 34272761, 2021). "Additionally, it was previously shown that C1 proteins of low concentration could significantly enhance the expression of interleukins IL-6, IL-8, and IL-10, which is in line with the finding that periodontitis patients have significantly higher salivary IL-6 levels than healthy subjects." (PMID 33498938, 2021). "As expected, induction of periodontitis led to the increased TNF and IL-6 expression in the gingival tissues." (PMID 34899728, 2021). "Serum‐based IL‐6, TNF‐α and IL‐1β, three different cytokines expression were demonstrated in PBMC of periodontitis and healthy controls." (PMID 34272761, 2021).
periodontitis (continued). "At the site of periodontitis, the levels of proinflammatory cytokines such as TNF-α, IFN-γ, IL-1, IL-6, IL-12 and G-CSF are significantly increased while anti-inflammatory cytokines are decreased (IL-4 and IL-10)." (PMID 34868054, 2021). "A recent systematic review reported that the interleukin-1 beta, interleukin-6, macrophage inflammatory protein-1 alpha, and matrix metalloproteinase-8 (MMP-8) levels are potential salivary biomarkers for the diagnosis of periodontitis." (PMID 34415974, 2021). "GCF from periodontitis patients had significantly higher concentrations of TNF-α, CCL2, IL-6, IFN-γ, and CXCL8 than controls." (PMID 34502071, 2021). "There are several reports pointing to the roles of IL-6 and nod-like receptor family pyrin domain-containing protein-3 (NLRP3), as a component of the innate immune system, in the pathogenesis of periodontitis." (PMID 34645448, 2021). "The concentrations of IL-1β, IL-6, and TNF-α were higher in periodontitis patients than in healthy controls." (PMID 34592963, 2021). "Resting PBMCs from patients with periodontitis secreted more IFN- γ, IL-6, IL-12p70, IL-17 and MCP-1 compared to healthy subjects." (PMID 34408814, 2021). "Proinflammatory cytokines, such as IL-1β, IL-6, and TNF-α, have been used as biomarkers to identify periodontitis and peri-implantitis." (PMID 34931168, 2021). "In the present study, IL-6 and IL-8 secretion by oral epithelial cells (GMSM-K cell line) was assessed following the exposure to filter-sterilized saliva from periodontitis or healthy subjects." (PMID 35048079, 2021). "The concentration of IL-1β, IL-6, and TNF-α was significantly higher in periodontitis patients than in healthy volunteers (P < 0.05)." (PMID 34592963, 2021). "Regarding intestinal tissue analyses, higher levels of IL-1β, IL-4, IL-6, IL-17A, IL17F, IL-21, IL-31, IL-33 and soluble CD40 ligand (sCD40L) were found in patients having IBD activity and periodontitis." (PMID 34501547, 2021). "Human studies have demonstrated that patients suffering from periodontitis exhibit higher concentrations of proinflammatory cytokines, such as tumor necrosis factor-alpha (TNF-α), C-reactive protein (CRP), interleukin-6 (IL-6) and Il-1β." (PMID 33804123, 2021). "After the periodontitis model establishment for 1 week, significantly increased mRNA expression of IL-1β, TNF-α, and IL-6 was observed in the IL-17 and IFN-γ groups than in the NS group (p < 0.05)." (PMID 34395635, 2021). "In AD model rats with induced periodontitis, compared to controls, TNF-α levels were significantly higher in the hippocampus, IL-1 levels were higher in the cerebral cortex, and IL6 levels were higher both in the hippocampus and cerebral cortex." (PMID 34769677, 2021). "We found that the GCF samples obtained from periodontitis patients contained significantly higher proportions of cytokines such as TNF-α, CCL2, IL-6, IFN-γ, and CXCL8 compared to the samples obtained from systemically and periodontally healthy controls." (PMID 34502071, 2021). "TNF-α, CCL2, IL-6, IFN-γ, and CXCL8 showed significantly higher levels in GCF from periodontitis patients compared to control subjects (p < 0.05)." (PMID 34502071, 2021). "Exposure of PBMCs to H2S triggered statistically significant higher levels of IFN-γ, IL-6, IL-17, and TNF-α secretion, both in the healthy group and in the periodontitis group." (PMID 34408814, 2021). "Previous studies have indicated that patients with periodontitis had the increased levels of serum and salivary NLRP3 and interleukin-6 (IL-6) in comparison with healthy controls." (PMID 34645448, 2021). "Under the irritation of periodontitis, human antigen-R (HuR) maintains the stability of IL-6 by binding to the 3′untranslated region (3′ UTR) of IL-6 mRNA." (PMID 34445604, 2021). "In the chronic phase of periodontitis, CD4+ T lymphocytes differentiate towards an anti-inflammatory Th2 profile, characterized by the production of IL-4, IL-5, IL-6, and IL-10." (PMID 34707462, 2021).
periodontitis (continued). "All of these results show that SPRC alleviated the progression of periodontitis by inhibiting proinflammatory cytokine (IL-17 and IL-6) expression and promoting anti-inflammatory cytokine (IL-10 and TGF-β) expression in a rat periodontitis model." (PMID 35087796, 2021). "The levels of salivary biomarkers, including IL-1, IL-6, and MMP-8, are reported to be significantly increased in patients with periodontitis in comparison with healthy controls." (PMID 33383828, 2020). "Significantly higher levels of serum of cytokines IL-6, TNF-α and IL-1β, IL10, IL35, and TGF-β1 were measured in patients with chronic periodontitis when compared to the healthy control group." (PMID 32604936, 2020). "F. alocis, a member of the genus Filifactor, is not only present at the site of periodontitis but has also been shown to induce the production of inflammatory cytokines such as TNF-α, IL-1β and IL-6 in vitro." (PMID 33121117, 2020). "A cohort study that included seven biomarkers showed that IL-1β, IL-6 and MMP-8 combination was the most sensitive and specific for discriminating health from periodontitis." (PMID 33081038, 2020). "The authors concluded that in the obese rat model, periodontitis increased the systemic LGI thereby upregulating the gene expression for hepatic levels of TNF-α and CRP and for IL-6 and CRP in the adipose tissue." (PMID 32486269, 2020). "The cluster of mediators susceptible to inhibition by I-BET151 and JQ1 in gingival fibroblasts and GECs includes IL-6, IL-1β, and CCL2, elevated levels of which are most commonly found in patients with periodontitis." (PMID 33256844, 2020). "The level of several other salivary cytokines, IL-6, IL-8, IL-17A, and tumour necrosis factor α (TNF- α) have been shown to be affected by periodontitis progress." (PMID 32646009, 2020). "In another study, the salivary macrophage inflammatory protein-1α, MM8, IL-1β, IL-6, prostaglandin E2 and TNF-α levels were reported to correlate with gingivitis and periodontitis development." (PMID 32646009, 2020). "In our periodontitis and AD rat models, the levels of TNF-α and IL-6 in the hippocampus, and IL-1 and IL-6 in the cerebral cortex of the Lig+AD group were significantly higher than those of the AD group." (PMID 32614834, 2020). "IL6, IL6R, IFNG, PTGS2, SOCS1, and TNF were identified as candidate genes that have been assessed for DNA methylation in periodontitis." (PMID 32867386, 2020). "In periodontitis, there is an increase in the production of proinflammatory mediators, such as IL-1β, TNF-α, IL-6, IFN-γ, and the levels of acute-phase proteins, such as CRP." (PMID 35919481, 2019). "Increased levels of pro-inflammatory mediators such as interleukin-6 (IL-6), C-reactive protein (CRP) and matrix metalloproteinase 9 (MMP-9) have been observed among people with periodontitis." (PMID 30873290, 2019). "LPS can induce the NF-κB signaling pathway activation to generate M1-related cytokines such as IL-6, TNF-α, IL-1β, and nitric oxide (NO) in macrophages during the progression of periodontitis." (PMID 31022963, 2019). "During the development of periodontitis, neutrophils release matrix metalloproteinase and proinflammatory cytokines including TNF-α, CCL2, and IL-6." (PMID 31781234, 2019). "Serum levels of proinflammatory cytokines such as IL-1β, IL-6, and TNF-α were increased in a rat ligature-induced periodontitis model." (PMID 29576800, 2018). "Consistent with previous studies, our results indicate that SHI down-regulates IL-1, IL-6, TNF-α, MMP-2, MMP-9 and COX-2 expression in LPS-stimulated hPDLCs, thus indicating the anti-inflammatory potential of SHI in the treatment of periodontitis." (PMID 30392422, 2018). "The purpose of this pilot study was to evaluate salivary levels of IL-6 and TNF-α according to periodontal status in pregnant women, in order to assess if the level of these pro-inflammatory cytokines could potentially be used as complementary diagnostic in pregnant women with periodontitis." (PMID 29740515, 2018).
periodontitis (continued). "In detail, IL-6 and TNF- α were only significantly increased in severe periodontitis compared to periodontal healthy groups." (PMID 29740515, 2018). "This study evaluated the expression of pro-inflammatory (IL-1β, IL-6, IFN-γ and TNF-α) and anti-inflammatory (IL-4 and TGF-β) cytokines in apical periodontitis lesions." (PMID 29898177, 2018). "Chronic periodontitis increases the amount of the systemic inflammatory mediators C-reactive protein (CRP) and interleukin-6 (IL-6), as well as total cholesterol and low-density lipoprotein (LDL) cholesterol levels." (PMID 30126459, 2018). "The maintenance of the inflammatory process is mediated by cytokines (TNF-α, IL-1β, IL-6, IL-8, IL-12, IL-17, IL-18, IL-23 and IFN-γ) in RA and in periodontitis." (PMID 30281626, 2018). "Higher levels of serum IL-6, C-reactive protein (CRP), TNF-α and IL-1β have been reported among periodontitis patients in several studies." (PMID 29980169, 2018). "The results of the study were demonstrative of increased IL-6, TNF-α, and visfatin levels in diabetic patients afflicted with periodontitis." (PMID 30186882, 2018). "Consistently higher levels of IL-6, IL-17, and IL-33 were detected in SLE patients with periodontitis." (PMID 28320468, 2017). "In two recent studies conducted with women immediately after delivery, GCF levels of IL-1β, IL-6, TNF-α, and PGE2 and serum levels of TNF-α and PGE2 were significantly increased in women with periodontitis compared with periodontally healthy women." (PMID 29017560, 2017). "In an experimental periodontitis model, the expression profile of HMGB1 has been shown to be similar to those of TNF-α and IL-6, with higher expression of those cytokines occurring at day 7 and 15 followed by a decrease on day 3012." (PMID 28765610, 2017). "These authors found evidence of significant differences between chronic periodontitis and periodontal health for only a few pro-inflammatory cytokines (IL1beta, IL6 and IL17, which showed higher levels for periodontitis than health)." (PMID 28912468, 2017). "There was a significant increase in inflammatory cytokines IL-6, IL-17, and IL-33 in saliva of SLE patients with periodontitis compared to control group with periodontitis." (PMID 28320468, 2017). "One of the main bacteria involved in periodontitis is Porphyromonas gingivalis, and its lipopolysaccharide (LPS) induce the expression of inflammatory cytokines TNF-α, IL-1β, and IL-6 and chemokines IL-8 in human gingival fibroblasts (HGF)." (PMID 28678155, 2017). "Changes in the oral microbiota were linked to increased local inflammation, as demonstrated by higher concentrations of IL-6, IL-17, and IL-33 in SLE patients with periodontitis." (PMID 28320468, 2017). "Multiple proinflammatory cytokines in the gingival crevicular fluid (i.e., IL‐1, IL‐6 and TNF‐α) have been found to correlate closely with the status of periodontitis; this finding greatly benefits the diagnosis, treatment and prognosis of periodontal disease." (PMID 26932392, 2017). "There is also evidence that gingival fibroblasts, challenged with A. actinomycetemcomitans from early-onset periodontitis (EOP) patients, are capable of secreting considerable amounts of IL-6 and IL-8 in vitro." (PMID 27807462, 2016). "For example, SRP decreased serum tumor necrosis factor-α (TNF-α), interleukin-6 (IL-6) and C-reaction protein (CRP) levels in chronic periodontitis subjects with stable coronary heart disease." (PMID 27386384, 2016). "TLR-2 and TLR4 play critical roles in recognizing periodontal pathogens and trigger the up-regulation of interleukin (IL)-6, IL-1β, and tumor necrosis factor (TNF)-α in periodontitis." (PMID 27529418, 2016). "Increased IL-6 levels have also been shown in GCF and saliva in periodontitis, as well as in periodontitis tissues." (PMID 26407063, 2015).
periodontitis (continued). "A consensus report of the 7th European Workshop on Periodontology recently highlighted interleukin (IL)-1β, IL-6, tumor necrosis factor (TNF)-α, and RANKL as important players in the periodontitis network." (PMID 26734583, 2015). "First threshold cutoff values for each analyte were based upon the population distribution for IL-1ß (≥28 pg/mL), IL-6 (≥5.5 pg/mL), MMP-8 (≥140 ng/mL), and MIP-1α (≥5 pg/mL) and selected to optimize sensitivity for detection of periodontitis." (PMID 26347856, 2015). "In serum, significant concentrations of IL-6 and TNF-α were present during the evolution of periodontitis and reactional lesions, while IFN-γ and IL-1β were related with T1R, T2R, and CPD." (PMID 26339136, 2015). "Therefore, reduction of the inflammatory mediators such as TNF-α and IL-6 (serum and/or GCF), which are also associated with both hyperlipidemia and periodontitis may provide a further contribution to a two-way relationship between periodontitis and hyperlipidemia." (PMID 26666260, 2015). "The present results demonstrate that diabetic patients with untreated periodontitis present increased circulating levels of markers of inflammation and proinflammatory cytokines (CRP, TNF-α and IL-6)." (PMID 26644840, 2015). "In this report, we use a selective voting ensemble classification approach (SVA) in conjunction with a battery of classification techniques and salivary biomarkers (IL-1ß, IL-6, MIP-1α, MMP-8) to discern clinically-labeled gingivitis and periodontitis groups." (PMID 26407063, 2015). "The IL-1β and IL-6 levels increased, whereas the TNF-β levels decreased with the severity of periodontitis (4 mm pocket percentage)." (PMID 25884025, 2015). "In agreement with the ability of APN to inhibit local chronic inflammation in our experimental periodontitis DIO model, we found gene expression levels of proinflammatory cytokines including TNF-α, IL-1, and IL-6 were significantly reduced in WAT tissues." (PMID 24836538, 2014). "The aim of the current study was to quantify IL-6, IL-8 and TNF-α levels and assess the correlation of these inflammatory markers in the human gingival tissues of patients with periodontitis." (PMID 24137277, 2013). "A panel of 8 SNPs in VEGF, ACT, HMG-CR, INF-γ, IL-1β, IL-10, IL-6 and TNF-α genes in patients with periodontitis and controls (CTR) was studied and genotype distributions and allele frequencies were obtained." (PMID 24274085, 2013). "Consistent with other inflammatory diseases, proinflammatory cytokines, including IL-6, IL-8 and TNF-α, appear to be major mediators in periodontitis." (PMID 24137277, 2013). "The aim of the present study was to quantify IL-6, IL-8 and TNF-α levels in the human gingival tissues of patients with periodontitis and to assess the correlation of these three cytokines with each other." (PMID 24137277, 2013). "The aim of this study is to compare genotypes and soluble protein of pro and anti-inflammatory cytokines (IL-1α, IL-1β, IL-6, IFN-γ, IL-10, TNF-α and IL-4) in subjects with or free of chronic periodontitis." (PMID 23046796, 2012). "In the gingival crevicular fluid, elevated IL-6, TNF-α, and IL-1β were reported in persons afflicted with periodontitis." (PMID 22315682, 2012). "Another common pathogenic link affecting periodontitis and RA is the monocytic hypersecretory state, which may induce the secretion of excessive pro-inflammatory cytokine secretion, such as IL-1b, TNF-a and IL-6, which results in the stimulation of degrading enzymes and tissue destruction." (PMID 22035090, 2011). "This study evaluated local and systemic levels of asprosin, tumor necrosis factor-α (TNF-α), and interleukin-6 (IL-6) in obese and normal-weight individuals with and without periodontitis." (PMID 41942957, 2026).